TNF (tumor necrosis factor)
Diseases named in the same sentence as TNF in open-access papers (continued):
Sharing a sentence is not in itself a finding about the gene and the disease.
chronic kidney disease (continued). "In addition, TNF-α was associated with a rapid renal function decline in the Chronic Renal Insufficiency Cohort Study." (PMID 34442425, 2021). "Chronic kidney disease (CKD) is associated with increased procoagulants, including cystatin C, C-reactive protein, interleukin-6, tumor necrosis factor-α soluble receptor 1, intercellular adhesion molecule-1, fibrinogen, and factor VIII." (PMID 30115029, 2018). "In subgroup analyses, chronic kidney disease significantly increased mortality among patients on TNF inhibitors." (PMID 40700294, 2025). "Chronic kidney disease is characterized by a persistent state of low-grade inflammation driven by elevated cytokines such as interleukin-6 (IL-6), tumor necrosis factor-α (TNF-α), and C-reactive protein (CRP)." (PMID 41552179, 2025). "IL-6 in combination with TNF-α facilitates the calcification of vascular cells to induce persistent low-grade systemic inflammation in chronic kidney disease (CKD) and progression of exacerbated diabetic nephropathy (DN)." (PMID 40733185, 2025). "Tumor necrosis factor-alpha (TNF-α), is partly attributed to pathogenesis of end-stage renal disease (ESRD)." (PMID 40048497, 2025). "As a uremic toxin, indoxyl sulfate is highly expressed in the serum of end-stage renal disease (ESRD) patients and has been reported to cause vascular damage through the TNF-α/CX3CL1 axis." (PMID 39996729, 2025). "In the Chronic Renal Insufficiency Cohort study, biomarkers of inflammation, such as IL-1β, IL-6, TNF-α, C-reactive protein, and fibrinogen, were inversely associated with measures of kidney function." (PMID 40048497, 2025). "In particular, this study in rats with adenosine-induced chronic renal failure showed that etanercept was able to significantly reduce serum TNF-α levels within 2 to 4 weeks of treatment." (PMID 40243751, 2025). "EVs extracted from umbilical cord-derived MSCs have attenuated TNF-α, IL-6, and IL-1β levels, and increased IL-10 level in a model of chronic renal failure following I/R injury." (PMID 40535418, 2025). "In the Chronic Renal Insufficiency Cohort (CRIC) study, biomarkers of inflammation (IL-1β, IL-1 receptor antagonists, IL-6, TNF-α, CRP, and fibrinogen) were negatively associated with renal function and positively associated with proteinuria." (PMID 39126619, 2024). "Chronic kidney disease features heightened levels of pro-inflammatory cytokines, including IL-1, IL-6, and TNF-α." (PMID 38766523, 2024). "Overproduction of proinflammatory cytokines (such as IL1, IL6, or TNF alpha) and reactive oxygen species in patients with chronic kidney disease is mediated by the activation of monocytes and macrophages." (PMID 38921685, 2024). "Chronic renal failure patients and animal models of acute kidney injury (AKI) caused by nephrotoxic drugs have shown increased levels of IL-6, IL-1β, and TNF-α." (PMID 39468702, 2024). "Studies have tied various pro-inflammatory molecules (e.g. tumor necrosis factor-alpha (TNF-α), interleukins 1β and 6 (IL-1β, IL-6) etc.)to the onset of chronic kidney disease (CKD)." (PMID 39469576, 2024). "A chronic inflammatory state induced by chronic kidney disease leads to proteolysis and appetite suppression in dialysis patients due to the release of cytokines such as interleukin-6 and tumor necrosis factor alpha." (PMID 37840653, 2023). "In fact, a clinical study reported that curcumin supplementation for 12 weeks markedly reduced plasma TNF-α levels in patients with chronic kidney disease undergoing hemodialysis." (PMID 37902021, 2023). "MTX-induced liver injury or chronic kidney disease in male Wistar rats pre-treated with chicoric acid reduced TNF-α, ROS, •NO, and malondialdehyde (MDA) levels." (PMID 36829986, 2023). "Chronic mediators of inflammation, such as tumor necrosis factor alpha (TNF-α), interleukin 6 (IL-6) and liraglutide, have shown increased levels in patients with chronic kidney disease." (PMID 37675359, 2023).
chronic kidney disease (continued). "Several traditional inflammatory cytokines, such as C-reactive protein (CRP), interleukin-6 (IL-6), and tumor necrosis factor-α (TNF-α), have been reported to aggravate kidney function impairment and increase the risk of death in patients with chronic kidney disease (CKD) and MHD." (PMID 37724554, 2023). "2,8-dihydroxyadenine crystal induced chronic kidney disease, in which TNF-α is involved in the pathogenesis, was established by oral adenine administration in C57BL/6JJcl mice (AdCKD) with or without SB to investigate its renal protective effects." (PMID 36849798, 2023). "Conversely, Hung and coworkers, including 338 chronic kidney disease patients in stages 3–5 in their study, demonstrated that hypervolemic patients not only had elevated IL-6 levels but also significantly increased TNF-α levels." (PMID 38139378, 2023). "In the PREDIAN study, it was observed that adding pentoxifylline to RAS blockade therapy led to a reduction in the urinary excretion of TNF-α, which was inversely related to the eGFR in patients with stage 3 and 4 chronic kidney disease." (PMID 37189380, 2023). "Effects of Shenkang injection (SKI) on the levels of CRP, IL-1β, IL-6, TNF-α, IL-4,and IL-10 in serum of chronic renal failure rats*." (PMID 35674582, 2022). "It reduced interleukin 6 (IL-6) and tumor necrosis factor-α (TNF-α), and played an important role in oxidative stress in a rat model of chronic renal failure." (PMID 36497603, 2022). "There have been many experimental studies and clinical observations showing that TNF-α and IL-6 also play a major role in the pathogenesis of chronic kidney disease through the induction of inflammatory processes." (PMID 35054932, 2022). "A clinical study showed an improvement in the renal function in patients with chronic kidney disease after Lac-B administration through decreasing of serum levels of TNF-α and IL-6." (PMID 36499631, 2022). "Co-administration of chrysin with adenine showed a significant decrease in the levels of TNF-α, IL-1β, sclerostin, and endothelin-1, indicating the ability of chrysin in attenuating adenine-induced chronic kidney disease through an anti-inflammatory mechanism." (PMID 36552226, 2022). "In this study, we employed the adenine-induced chronic kidney disease (Ad-CKD) model to produce rapid-onset kidney disease in rats to assess the effects of ETA on TNF inhibition and its impact on progressive kidney failure." (PMID 35647193, 2022). "Chronic kidney disease (CKD) constitutes a chronic inflammatory state associated with an increase in inflammatory mediators and profibrotic molecules such as tumor necrosis factor-α (TNF-α)." (PMID 35647193, 2022). "In some studies, elevated level of IL-18 was paired with increase in TNF-alpha in chronic kidney disease." (PMID 36558477, 2022). "Chronic inflammatory states are commonly found in patients with end-stage renal disease, and inflammatory cytokines, including IL-6, IL-1, TNF-a and CRP play an important role." (PMID 33413177, 2021). "Increased serum or plasma concentrations of inflammatory markers, including CRP, interleukin 6 and TNFα are consistently reported in patients with chronic kidney disease." (PMID 34827620, 2021). "Supplementation of HAM-RS2 led to a decrease in serum IL-6 and TNFα in end-stage renal disease patients." (PMID 34354689, 2021). "Activation of the complement cascade and pro-inflammatory cytokines (CK) such as Tumor Necrosis Factor α (TNF-α) and Interleukin-6 (IL-6) can alter GFB function, causing acute glomerular injury and progression toward chronic kidney disease." (PMID 34359843, 2021). "Among the OCTs, OCT2 was found consistently downregulated in the kidney of rats with chronic kidney disease (CKD) or acute kidney injury (AKI) and in patients diagnosed with CKD, and it was associated with the upregulation of TNFα renal expression." (PMID 35059420, 2021).
chronic kidney disease (continued). "IL-1β, IL-6, and TNFα are important cytokines that serve as essential mediators of the immune response and inflammatory reactions in patients with chronic renal failure." (PMID 34463195, 2021). "A recent cohort study involving 3430 patients with chronic renal insufficiency also found that increased levels of TNF-α and decreased serum albumin in patients with chronic renal disease were associated with rapid loss of renal function." (PMID 34992536, 2021). "Plasma pro-inflammatory biomarkers such as TNF were increased in CKD patients in the Chronic Renal Insufficiency Cohort study." (PMID 32660446, 2020). "In concomitance, the diabetic patients with end-stage renal disease also showed higher levels of serum inflammatory cytokines TNF-α, IL-6, and IFN-γ." (PMID 33442388, 2020). "A study conducted in patients with chronic renal insufficiency revealed that kidney injury was positively correlated to the levels of proinflammatory cytokines, namely, tumor necrosis factor alpha (TNF-α) and interleukin-6 (IL-6) in the plasma." (PMID 32292787, 2020). "Similar observations have been previously reported for VD on oxidative stress markers and the expression of IL-10, IL-4 and TNF-α in chronic renal diseases and testicular dysfunction." (PMID 29556070, 2018). "The adverse effects of a high sodium intake on the inflammation marker tumor necrosis factor-α were also observed in Sprague Dawley rats with chronic renal failure." (PMID 27706075, 2016). "Canine leptospirosis was characterized by high 5-LO and low TNF-α expression compared to other causes of acute kidney injury, although the decreased TNF-α expression was also seen in chronic kidney disease." (PMID 26824356, 2016). "BSHX protects 5/6 nephrectomy rats against chronic renal failure probably via regulating the expression of TNF-α, NF-κB, TGF-β1, CTGF, PPARγ, OPN, fibronectin, and laminins and is useful for therapy of CRF." (PMID 24864155, 2014). "In patients with end-stage renal disease, higher levels of proinflammatory cytokines such as tumor necrosis factor alpha (TNFα) and interleukin-6 (IL-6) have been consistently observed and are thought to contribute to ACD." (PMID 23053592, 2012). "In patients with chronic kidney disease, elevated serum TNF-α levels demonstrate a significant association with increased hospitalization risk due to UTI, suggesting that TNF-α may exacerbate infection susceptibility through impaired immune regulation." (PMID 41357523, 2025). "Documented risk factors, including alcoholic liver disease, HIV infection, malignancy, anti-TNF therapy, and patients with end-stage renal disease undergoing continuous ambulatory peritoneal dialysis, promote cellular immune dysfunction, heightening susceptibility to TB." (PMID 40642668, 2025). "Moreover, cytokines like IL-6 or TNF can drive an inflammatory process by inducing COX-2 expression in chronic kidney disease." (PMID 40217316, 2025). "This can increase the expression levels of miR-29a and miR-29b, which may improve malnutrition and reduce tumor necrosis factor-α (TNF-α) as an oral nutritional agent for chronic kidney disease." (PMID 39123577, 2024). "Male rat mesangial cells exhibit naturally higher baseline levels of fibronectin, TNF- α, and interleukin-1 beta (IL-1β) compared to female cells, which may play a role in the quicker advancement of chronic renal disease in males." (PMID 39124622, 2024). "Tumor necrosis factor-alpha (TNFα) is a major proinflammatory and tissue damaged promoting cytokine, which has been implicated in inflammatory renal tissue injury during pathological conditions associated with chronic kidney disease (CKD) or acute kidney injury." (PMID 39871891, 2024). "Thus, further studies are necessary to examine if TNF-α is elevated in hypervolemic patients with chronic kidney disease." (PMID 38139378, 2023).
chronic kidney disease (continued). "In this study, we focused on identifying the levels of gum-disease-causing bacteria and their byproducts, namely, TNF alpha in patients with or without chronic kidney disease." (PMID 35336824, 2022). "Chronic kidney disease (CKD) is associated with low-grade inflammation and increases the serum concentration of inflammatory markers, such as C-reactive protein, cytokines, TNF α, and adhesion molecules." (PMID 36012158, 2022). "This negative relationship between TNF- α and melatonin levels in saliva and its association with sleep has been observed, in patients with chronic renal failure." (PMID 33579032, 2021). "Indeed, EET-A has previously been demonstrated to decrease renal inflammatory cell infiltration and levels of monocyte chemoattractant protein-1 (MCP-1), TNF-α, IL-6, and IL-1β in acute and chronic kidney disease models." (PMID 33801911, 2021). "A study showed that patients with chronic kidney disease with lower eGFR levels had higher levels of plasma IL-1 β, IL-1RA, IL-6, TNF-α, hypersensitive CRP, and fibrinogen and that the inflammation score was inverted with GFR estimates and urinary albumin/creatinine ratio (UACR)." (PMID 34992536, 2021). "ADAM17, one of the most studied ADAMs family members, contributes to the development of chronic kidney disease by activating inflammatory and proliferative processes through Tumor Necrosis Factor alpha (TNF-α) and Endothelial Growth Factor Receptor (EGFR) signaling pathways." (PMID 34884897, 2021). "Results of the Chronic Renal Insufficiency Cohort (CRIC) showed that higher FGF23 levels are associated with higher levels of the inflammatory markers CRP, IL6, TNFα, and fibrinogen and with a higher odds ratio for severe inflammation independent of mineral metabolism and renal function." (PMID 34208131, 2021). "It has been reported in the pathogenesis of chronic kidney disease, and excessive ROS has been reported to activate mediator signalling molecules which trigger the production of inflammatory cytokines such as IL-1β or TNF-α." (PMID 32975098, 2020). "IgA nephropathy (IgAN) is a rather uncommon complication of TNF-alpha inhibition with a range of findings such as asymptomatic microscopic/macroscopic hematuria or different degrees of proteinuria and could progress to end-stage renal disease." (PMID 32373375, 2020). "Therefore, TNF-α has also been proposed as one of the key adipokines in the progression of renal injury and chronic kidney diseases." (PMID 29636702, 2018). "TNF-α/NF-kB are promising targets for developing novel chronic kidney disease drugs." (PMID 28270699, 2017). "Another study was conducted among 16 patients suffering from chronic kidney disease to evaluate the anti-inflammatory effect of a curcuminoid and found to be mediated by regulating the inflammatory mediators such as IL-6, IL-8, TNF-α, TNF-ß, substance P, hs-CRP, CGRP, and MCP-1." (PMID 29029547, 2017). "Additionally, clinical studies have demonstrated that calcitriol treatment suppressed IL-6 and TNF-α expression in patients with chronic kidney disease." (PMID 25823676, 2015). "A study was done to determine the levels of resistin, adiponectin, and other inflammatory markers in subjects with chronic kidney diseases with those of control subjects, and it was found that subjects with chronic kidney diseases have increased levels of resistin and TNF-α." (PMID 24692844, 2014). "Interestingly, in patients with DN, the levels of serum TNF-α and its receptor are elevated and are indicative of both renal functional decline and progression to end-stage renal disease, and inhibiting TNF-α notably alleviated glomerular lesions in murine models of DN." (PMID 38786068, 2024). "Moreover, high levels of TNF induce inflammatory injury in the kidney, which contributes to renal vasoconstriction by increasing superoxide generation and a subsequent reduction in the glomerular filtration rate, eventually leading to chronic kidney disease." (PMID 37784156, 2023).
chronic kidney disease (continued). "A search in Pubmed was conducted, including animal and human studies, using the keywords “renal disease”, “chronic kidney disease”, or “CKD”, and the biomarkers name “TNF-α”, “TNFR1”, and “TNFR2”, to search the title and/or abstract." (PMID 35328704, 2022). "In a large cohort of patients with chronic kidney disease (the Chronic Renal Insufficiency Cohort—CRIC—study), faster progression of kidney insufficiency was shown to be positively associated with chronic inflammation and increased inflammatory markers, including interleukin 6 and TNFα." (PMID 34827620, 2021). "Treatment with an IκB kinase inhibitor attenuated sepsis-induced cardiac dysfunction with chronic kidney disease (CKD) via reduced expression of inflammatory cytokines (TNF-α, IL-1β, IL-6, and IL-10)." (PMID 32581829, 2020). "Among them, tumor necrosis factor alpha (TNF-α), interleukin-6 (IL-6), neopterin, ferritin, C-reactive protein (hs-CRP) and the complete blood count changes are considered as most valuable predictors of all-cause mortality risk from CVD events in chronic renal insufficiency conditions." (PMID 30617956, 2019). "Using a reciprocal approach we demonstrated that conditioned medium from MMECs over expressing eNOS protected podocytes from TNF-α-induced injury, suggesting that glomerular endothelial cells may also play a protective role in the pathogenesis of chronic kidney disease." (PMID 23359116, 2013). "Patients with chronic kidney disease (CKD) exhibit elevated CD14++CD16+ pro-inflammatory monocytes in bone marrow alongside heightened systemic levels of IL-6, IL-1β, and TNF-α, suggesting persistent innate immune activation." (PMID 40746537, 2025). "For example, in chronic kidney disease (CKD), the increased expression of GPR68 on human monocytes promotes the release of TNF-α, IL-6, and other pro-inflammatory cytokines, which aggravate systemic inflammation and fibrosis." (PMID 41190345, 2025). "The chronic kidney disease group exhibited elevated serum urea and creatinine and reduced eGFR, along with increased levels of KIM-1, NGAL, IL-18, TNF-α, IL-6, NF-κB, and FMO3." (PMID 40978750, 2025). "Monocytes from end-stage renal disease (ESRD) patients have increased ALOX5 expression and after 6 days training, they exhibit enhanced TNF-α and IL-6 production to lipopolysaccharide (LPS)." (PMID 38980302, 2024). "IS, a bacterial metabolite of tryptophan, exhibits pro-inflammatory effects in chronic kidney disease (CKD) patients: it increases inflammatory cytokines (TNF-α, IL-6, and TGF-β1) and ROS levels in C2C12 cells, accelerating skeletal muscle atrophy and negatively affecting muscle strength." (PMID 38891777, 2024). "Patients with chronic kidney disease (CKD) display higher serum levels of oxLDL, characterized by an hyperinflammatory phenotype of monocytes accompanied by an increased production of pro-inflammatory cytokines (i.e., TNF-α, IL-1β and IL-6)." (PMID 36979747, 2023). "Chronic kidney disease (CKD) and HF involve chronic inflammatory mechanism, with several pro-inflammatory biomarkers, including tumor necrosis factor-α (TNF-α), initiating spreading inflammatory cascades." (PMID 37214467, 2023). "With the progression of chronic renal failure, the level of CRP, and TNF-α in patients’ serum are showing an up ward trend." (PMID 38152332, 2023). "One study of chronic kidney disease revealed higher systemic inflammatory marker levels, such as C-reactive protein (CRP), interleukin (IL)-6, and tumor necrosis factor-α, in patients with low GNRI scores than those with high GNRI scores." (PMID 37799767, 2023). "ANP has been identified recently as being associated with chronic kidney disease (CKD) without diabetes through the stimulation of secretion of cytokines (IL-6, TNF-α) and adiponectin." (PMID 35466213, 2022). "Elevated levels of pro-inflammatory cytokines including TNFα have been reported in the general CKD population and in end stage renal disease." (PMID 31095586, 2019).